RN7SL320P (RNA, 7SL, cytoplasmic 320, pseudogene)
Gene: Miscellaneous RNA gene on chromosome 13 (51,469,753 to 51,470,047, forward strand). Ensembl gene ENSG00000243900.
Homologues: Orthologues: chimpanzee Metazoa_SRP (99% identical), macaque Metazoa_SRP (92% identical). Paralogues in human: RN7SL1 (83% identical), RN7SL2 (82% identical), RN7SL296P (81% identical), RN7SL126P (81% identical), RN7SL3 (81% identical), RN7SL441P (81% identical), RN7SL130P (81% identical), RN7SL45P (80% identical), RN7SL709P (80% identical), RN7SL868P (80% identical), RN7SL680P (80% identical), RN7SL300P (80% identical), and 701 more.